INS (insulin)
Diseases named in the same sentence as INS in open-access papers (continued):
Sharing a sentence is not in itself a finding about the gene and the disease.
Insulin resistance (continued). "What is not known is whether stressors influence insulin secretion and/or insulin resistance in chickens." (PMID 38473137, 2024). "Homeostatic model assessment for insulin resistance (HOMA-IR) revealed that sucrose fatty acid esters and CMC increased the HOMA-IR index, suggesting that the intake of the emulsifiers sucrose fatty acid esters and CMC dysregulated glucose and insulin homeostasis." (PMID 38902371, 2024). "Taurine could improve insulin resistance by activating the PI3K/AKT/GLUT4 pathway in HFD/STZ-induced T2DM rats and PA-induced IR-HepG2 and the regulatory effects of taurine on the insulin signaling pathway in the liver, the target organ of insulin." (PMID 38799166, 2024). "Furthermore, HOMA-IR and AdipoIR were not compared because both measures use insulin as factor in the calculation of insulin resistance values." (PMID 38491191, 2024). "Insulin induces insulin resistance in human DPSCs and effectively promotes their proliferation, osteogenic differentiation and bone formation capability through gradually inducing the down-regulation of IIS/PI3K/AKT/mTOR pathway axis under insulin resistant states." (PMID 39075596, 2024). "However, the absence of P2Y13-R favored insulin resistance, which was evident from the increased basal and glucose-stimulated insulin levels and resulted in a higher insulin resistance index." (PMID 38470490, 2024). "Notably, OVX + DHT mice displayed decreased insulin sensitivity during an ITT compared to the other three groups that did not display insulin resistance." (PMID 37872876, 2024). "In this study, no change in insulin or various insulin resistance indices (HOMA, QUICKI, and RQUICKI) were observed in response to BCA or BCK, which could be because blood samples were collected after a short fasting period (~ 3 h)." (PMID 38281954, 2024). "However, it appears that insulin does not totally compensate for extreme insulin resistance — thus there is a measurable deviation from the hyperbolic relationship at very reduced SI values." (PMID 38299589, 2024). "Compared to usual care, OSA therapy with continuous positiveairway pressure (CPAP) or implantation of a mandibular advancement device, improves insulin resistance without changing BMI, supporting a role fortissue hypoxia in the pathogenesis of insulin resistance." (PMID 39076340, 2024). "Androgens appear to decrease highly oxidative and insulin-sensitive type I muscle fibers and increase glycolytic and less insulin-sensitive type II fibers in non-athletes, further promoting the development of insulin resistance." (PMID 38180081, 2024). "Insulin may contribute to immunomodulatory events by regulating the activation of the NLRP3 inflammasome in monocyte-derived macrophages, but there is also a direct link between insulin resistance and increased NLRP3 expression." (PMID 39200288, 2024). "Our results showed that DC mice had abnormalities in the relevant indices of insulin metabolism (including FINS, HOMA-IR, HOMA-β, and ISI), and islet cell shrinkage and reduced number were also found in HE staining of the pancreas, resulting in insulin resistance." (PMID 39063287, 2024). "Knockdown of lncRNA AK044604 (regulator of insulin sensitivity and autophagy, RISA), a regulatory factor, regulates insulin sensitivity and autophagy in mice, increases the phosphorylation of ULK1, and thus helps initiate autophagy and weaken insulin resistance." (PMID 38338839, 2024). "Despite extensive research, no (plausible) mechanism can be identified to explain how insulin resistance could be responsible for increased insulin secretion in subjects with a normal glucose tolerance." (PMID 38791525, 2024). "Both diabetics and non-diabetics can exhibit insulin resistance and elevated insulin levels." (PMID 38172731, 2024).
Insulin resistance (continued). "Furthermore, there was also a marked improvement of HOMA-IR (1.69 vs3.64) accompanied by an over 50% fall in insulin concentrations during GST,indicating an OCP-related induction of insulin resistance (IR), most likely relatedto alterations in cortisol metabolism." (PMID 39700335, 2024). "A study has found that DHM (1.0 g and 0.5 g/kg, BW) could reduce fasting blood glucose, serum insulin, glycosylated hemoglobin levels, and HOMA-IR index, and upregulate IRS-1 (Y612) tyrosine phosphorylation, finally improving insulin resistance in fatty db−/db− mice." (PMID 38275711, 2024). "Studies in mouse models have shown that, in the absence of hyperglycemia, increased insulin levels and insulin resistance might lead to lower bone turnover and higher areal BMD." (PMID 38172731, 2024). "Additionally, it also has been documented that the utilization of HucMSC-Exos has the potential to reinstate the structural integrity of islets, augment insulin sensitivity by the facilitation of glucose uptake through GLUT1–4, as well as diminish the insulin resistance in rats with T2DM." (PMID 38632264, 2024). "Finally, due to the lack of data on fasting insulin levels, it is currently not possible to compare the TyG index with other gold standard indices for evaluating insulin resistance." (PMID 38702717, 2024). "Data previously suggested that elevated cardiac acetaldehyde exposure via ADH may exacerbate alcohol‐induced myocardial dysfunction, hypertrophy, and insulin sensitivity, indicative of a key role of ADH proteins in insulin resistance and alcohol‐induced cardiac dysfunction." (PMID 38420755, 2024). "Despite a role in sex-specific changes, DNA methylation does not appear to be the major driving force in gene expression differences related to insulin resistance or the reduced ability of insulin to stimulate glucose uptake in I-Res cells, since neither of these were changed by 5-Az treatment." (PMID 38032738, 2024). "Therefore, although protein synthesis regulation shows a beneficial role in alleviating ER burden and modulating insulin sensitivity, it fails to reflect a comprehensive state of cellular insulin resistance." (PMID 39749015, 2024). "While insulin remained within the reference interval (12–96 ​pmol/L (Amsterdam UMC)) and is not of clinical significance on its own, alongside reductions in fasting blood glucose and HbA1c, the decrease supports the intervention's effect on reducing insulin resistance." (PMID 39435357, 2024). "Although the remaining islet cells could still secrete insulin, the blood glucose level did not decrease, indicating that the mice had insulin resistance." (PMID 38257160, 2024). "We detected no alterations in fasting circulating glucose or insulin or the homeostasis model assessment score of insulin resistance (HOMA-IR), measured at several time points during the period of high-fat diet consumption when comparing Mst4–/– mice and wild-type controls." (PMID 38397122, 2024). "Additionally, dendrobine might affect cell signal transduction by influencing genes like AKT1, STAT3, potentially related to KEGG pathways such as “insulin resistance”, “PPAR signaling pathway”, and “insulin signaling pathway”." (PMID 38755697, 2024). "From this perspective, calorie restriction could reduce the risk of developing T2D, or promote its remission if already established, by increasing insulin secretion rather than alleviating insulin resistance." (PMID 38942960, 2024). "To determine which organs were responsible for systemic insulin resistance in MBCUCP1 KO mice, we assessed AKT phosphorylation as a marker of insulin signaling in peripheral metabolic organs collected from MBCUCP1 KO mice and controls that received bolus insulin on a fasted condition." (PMID 38653240, 2024).
Insulin resistance (continued). "IGF-I’s effects on the liver may involve mechanisms, such as improved insulin sensitivity, as IGF-I deletion from the liver results in insulin resistance, suggesting that increased levels of circulating IGF-I can alleviate MASH partly by enhancing insulin sensitivity." (PMID 39452494, 2024). "During the insulin tolerance test (ITT), the blood glucose decay rate was slower in LS–S mice when compared to the other groups, as previously reported, suggesting peripheral insulin resistance elicited by the dietary sodium restriction, which was prevented by the AET (LS–T group)." (PMID 39337664, 2024). "This may suggest that the presence of good fat in the diet can either prevent insulin resistance or even promote insulin sensitivity, irrespective of the percentage of fat or calorie intake." (PMID 38414818, 2024). "It is possible that the growth-promoting MAPK pathway, which predominates in vascular SMCs and is hypothesized to be unaffected or even potentiated by hyperinsulinemia in conditions of insulin resistance, was not activated by insulin in our in vivo conditions." (PMID 39195275, 2024). "Whereas the effects of HIIT alone or in combination with DS on fasting glucose and insulin, as the indicators of insulin resistance, without the effects of HIIT + DS on adipokines were assessed by two studies, which, interestingly, had chosen similar HIIT protocols and vitamin D3 supplementation." (PMID 38337640, 2024). "Fasting glucose greater than 6.1 mmol/L, insulin greater than 11.78 mU/L, and homeostatic model assessment for insulin resistance (HOMA-IR) greater than or equal to the 75th percentile were categorized as hyperglycemia, hyperinsulinemia, and high insulin resistance, respectively." (PMID 38173399, 2024). "AUC of OGTT, serum insulin levels and HOMA-IR all notably increase in the model group, but evidently decrease after administration of HPM, which further demonstrates that HPM possess the effect of improving pancreatic beta cell function and alleviating insulin resistance." (PMID 39201413, 2024). "Further evaluation of insulin resistance and glycosylated hemoglobin levels using the homeostatic model of insulin showed an upsurge in insulin and hemoglobin levels and peroxisome proliferator‐activated receptor c (PPARc) and GLUT4 expression at protein levels in insulin‐dependent tissues." (PMID 39619995, 2024). "The mechanism of Chelerythrine in retaining the benefits of improving insulin sensitivity while reducing adverse reactions of thiazolidinedione shows that chelerythrine is a very promising drug, which can selectively target PPAR γ to further develop the clinical treatment of insulin resistance." (PMID 36755923, 2023). "Accumulation of the non-canonical NF-κB-inducing kinase (NIK) in obesity drives insulin resistance in the liver and muscle and impairs insulin secretion in pancreatic beta cells, whereas deletion of Map3k14, which encodes NIK, renders mice hypoglycaemic and improves glucose tolerance." (PMID 37311878, 2023). "We have recently shown that in patients with HCV treated with paritaprevir/ritonavir/ombitasvir/dasabuvir (PrOD), with or without ribavirin, fasting glucose, insulin, and Homeostatic Model Assessment of Insulin Resistance (HOMA-IR) are unchanged during treatment and follow-up after treatment." (PMID 36472923, 2023). "It is characterized by insulin resistance and high glucose levels due to β cell dysfunction in the pancreas where insulin is produced but insulin receptors do not respond or insulin-responsive cells poorly respond to insulin." (PMID 37894880, 2023). "The heterogeneity of insulin secretion by the HFD-fed mice at 20 weeks of age may be influenced by the ad libitum consumption of the HFD diet at night and differences in mouse-specific insulin resistance." (PMID 36780539, 2023).
Insulin resistance (continued). "Insulin resistance (IR) is a pathophysiological condition in which organs—mostly skeletal muscle, adipose tissue, and liver—do not respond at an adequate rate to insulin, and it is considered to be a consequence of the disruption of different molecular pathways affected by insulin in these tissues." (PMID 37443718, 2023). "Blood glucose levels after lunch in individuals with overweight may be even higher than in individuals without overweight due to inadequate compensatory insulin secretion for the elevation of insulin resistance." (PMID 36909337, 2023). "However, there are also additional practical and feasible indirect methods that do not require serum insulin levels to approximate insulin resistance status." (PMID 37671195, 2023). "In the “increasing” group of the present study, which included subjects with normal or mildly affected glucose tolerance, there was a tendency towards enhanced IGI and oDI without a concomitant change in insulin resistance as determined by HOMA-IR or fasting insulin." (PMID 37623862, 2023). "Finally, these studies also reveal that increasing FOXA2 levels in islets with reduced mTORC1 activity rescue PDX1 levels and insulin secretion, highlighting the importance of the AKT/FOXA2/PDX1 axis as a possible therapeutic tool to improve β-cells in conditions of insulin resistance." (PMID 37423392, 2023). "However, fasting insulin (P = 0.81) and homeostatic model assessment for insulin resistance (HOMA-IR) (P = 0.93) were not significantly different when comparing two groups during the study in the raw and even adjusted models." (PMID 37605174, 2023). "PTP1B inhibitors enhance insulin and leptin signaling and could potentially improve insulin resistance, normalizing plasma glucose and insulin levels without inducing hypoglycemia." (PMID 38139019, 2023). "Since insulin resistance is a primary pathophysiology of PCOS, dyslipidemia in PCOS‐afflicted women may be consistent with cases of the condition that have been documented in an insulin resistant state." (PMID 37985173, 2023). "First, in women with recent gestational diabetes, worsening hepatic insulin resistance in the 1st year postpartum has been shown to independently predict declining beta-cell function, while concurrent changes in whole-body insulin sensitivity (Matsuda) and weight did not do so12." (PMID 37500612, 2023). "Indeed, insulin has an anti‐inflammatory effect in some, but not all studies pertaining to people with insulin resistance." (PMID 36597186, 2023). "Regarding the treatment of HNF1B/MODY, patients present hepatic insulin resistance to some extent, and thus the treatment with oral hypoglycemic agents such as sulfonylureas may not be satisfactory, and early insulin therapy may be requested." (PMID 36672242, 2023). "Similarly, this research showed that there is a positive and significant correlation of WC with weight, HP WHR, BMI, NC, insulin, and insulin resistance index, and a negative correlation with adiponectin and HDL-C only in women." (PMID 37456476, 2023). "Although the blood glucose level in these individuals is in the normal range, high levels of fasting blood insulin level (60 ± 33 pmol/l in NGT/obese vs 25 ±7 pmol/l in NGT/non-obese) indicates insulin resistance in this group, which is compensated by more insulin secretion." (PMID 37319295, 2023). "Therefore, it is likely that in subjects with severe NAFLD (most of whom had insulin resistance), the exercise we proposed was not sufficiently intense to produce positive changes in insulin levels." (PMID 37242135, 2023). "Thus, in the setting of insulin resistance in T2DM, the decreased insulin signaling and enhanced PARs activation may increase gastric tissue damage due to reduced PI3K/Akt activity and enhanced inflammatory responses." (PMID 37228689, 2023).
Insulin resistance (continued). "Additionally, a one-year intervention with flavan-3-ols and isoflavones (850 mg/d and 100 mg/d, respectively) markedly reduced estimated peripheral insulin resistance (HOMA-IR) and enhanced insulin sensitivity due to a notable decrease in insulin levels in post-menopausal women with type 2 diabetes." (PMID 37513660, 2023). "Our study could not demonstrate a significant difference between the MET groups in T1DM subjects, possibly because physical activity reduces insulin resistance and not insulin secretion as in T1DM." (PMID 38239414, 2023). "The relation of miR146a with insulin and glucose metabolism indicators in the present study, suggests that it might be a response to insulin resistance that is not effective in reducing insulin sensitivity." (PMID 37917636, 2023). "Instead, they might have a more favorable response to medications that target insulin resistance (e.g., metformin) rather than those that primarily stimulate insulin secretion." (PMID 37915365, 2023). "However, in conditions of genetic insulin resistance such as Rabson–Mendenhall syndrome under insulin therapy, empagliflozin improved glycemic control without significantly increasing ketonemia." (PMID 37152929, 2023). "TNFα activates the phosphorylation of tyrosine in the insulin resistance (IR) and insulin receptor substrate molecule (IRS) signaling pathways by TNFα-induced kinases, such as c-Jun N-terminal kinase or IkB kinase, which impede the progression of the insulin pathway." (PMID 38137918, 2023). "Whilst it is acknowledged that variation between insulin assays means that direct comparison of HOMA-IR values between studies is not always appropriate, differences in the degree of fasting insulin resistance demonstrated by different study cohorts theoretically could impact the findings." (PMID 36771271, 2023). "Basal and ATP-linked respiration showed a negative correlation with fasting insulin levels and the HOMA index, reinforcing the long-known role of mitochondrial dysfunction in the pathophysiology of insulin resistance and associated metabolic complications in liver and other organs." (PMID 37510108, 2023). "Furthermore, global but not brown adipocyte-specific PINK1 KO mice exhibit insulin resistance, suggesting that mitophagy functions differently in maintaining insulin sensitivity in WAT and BAT." (PMID 37582956, 2023). "The measurement of serum insulin levels in patients who were not administered insulin might provide more information regarding the changes in insulin resistance." (PMID 37165443, 2023). "In the case of insulin resistance, we divided all the subjects into two groups: those with a HOMA-IR index above 2.0 and those with a HOMA-IR index below 2.0 (according to the following formula: HOMA-IR = (FPG × fasting serum insulin)/405, assuming <2 as normal in adults)." (PMID 37373485, 2023). "In addition, there have also been studies showing that the effect of tacrolimus is stronger than that of cyclosporine, tacrolimus can decrease insulin secretion without altering insulin resistance, and its effect on insulin secretion is dose-dependent." (PMID 36843576, 2023). "Among the measured parameters, fasting blood glucose levels, hemoglobin A1C, insulin activity, and Homeostatic Model Assessment for Insulin Resistance (HOMA-IR) were significantly different between the two groups, with higher values in diabetic patients with insulin resistance (p<0.0001)." (PMID 38107710, 2023). "Moreover, increases in fasting insulin levels and insulin resistance were reported in three British Asian patients with non-insulin-dependent diabetes and vitamin D deficiency after three months of vitamin D administration." (PMID 37111216, 2023).